AFP (alpha fetoprotein)
Diseases named in the same sentence as AFP in open-access papers (continued):
Sharing a sentence is not in itself a finding about the gene and the disease.
viral hepatitis (continued). "When conducting a subgroup analysis of the viral hepatitis cohort, the number of AFP tests performed (HR = 0.96, 95% CI: 0.95–0.96), as well as receiving antiviral treatment, were identified as independent protective factors for developing HCC." (PMID 38201578, 2023). "Mizejewski (2015) discussed a possible role of human AFP as a positive inflammatory reactant in the prenatal phase or chronic viral hepatitis, and Prell (2016) reported significantly higher AFP levels in septic neonates in comparison to healthy ones." (PMID 36495211, 2023). "AFP [OR: 131.79 (95% CI 3.41, 5092.94), p = 0.009], viral hepatitis [OR: 50.78 (95% CI 3.54, 727.86), p = 0.004] and sonographic score [OR: 3.72 (95% CI 1.56, 8.91), p = 0.003] were independent factors that distinguish HCC and IPT." (PMID 34692513, 2021). "SCCA-1 has previously shown promise, particularly as an AFP complementary biomarker, in viral hepatitis related HCC." (PMID 18638391, 2008). "When combined with AFP it has a sensitivity of up to 82% for HCC detection on a background of viral hepatitis." (PMID 18638391, 2008). "Moreover, AFP levels can be falsely elevated in patients with chronic liver disease or viral hepatitis, resulting in a notable rate of false positives." (PMID 39682122, 2024). "It was gradually increased that age, the proportion of females, non-viral hepatitis-related causes, AFP-negative, and abnormal glucose/lipids among PLC patients." (PMID 36998463, 2023). "The disparate utility of AFP testing in viral hepatitis patients versus patients with alcohol use disorder may be attributable to differences in the etiology and pathogenesis of HCC." (PMID 38201578, 2023). "Moreover, despite AFP being the strongest studied biomarker, it is by itself insufficient for surveillance, particularly in the setting of HCC related to viral hepatitis, the most common underlying etiology in Africa." (PMID 36277115, 2022). "With AFP, viral hepatitis, and sonographic score, the probability of HCC could be estimated for each patient." (PMID 34692513, 2021). "Mild elevation of AFP has also been found to correlate with viral hepatitis especially hepatitis C." (PMID 18842148, 2008). "In ALD/NAFLD patients, where a mild to moderately elevated but stable AFP level similar to that occasionally observed in individuals with viral hepatitis is rare, it may be possible to attach a more sinister connotation to much lower levels of expression." (PMID 18638391, 2008). "In contrast, age, viral hepatitis, recurrent type, ALBI score, AFP, tumor diameter, tumor number, and RFA were identified as risks associated with RFS in univariate analyses." (PMID 33675382, 2021). "Patients with viral hepatitis were more likely to be younger, male, and African American (p < 0.05) and had lower comorbidity indices, lower AJCC staging, higher median AFP, and decreased median tumor size (p < 0.05)." (PMID 34318618, 2021). "In chronic viral hepatitis, the GALAD model showed superior performance in detection of early-stage HCC, while exhibiting higher specificity in HCV patients compared to AFP alone." (PMID 34451832, 2021). "Although AFP alone has poor sensitivity for early stage HCC and poor specificity in patients with viral hepatitis, several studies have suggested a potential benefit of using AFP as an adjunct surveillance test with ultrasound." (PMID 32944652, 2020). "The most commonly used tumour marker alpha-feto protein (AFP) has a rather low sensitivity and specificity of only 40–65% and 76–96%, subject to the cut-off value and the presence of viral hepatitis." (PMID 29875798, 2018). "His serum alpha fetoprotein (AFP) was 1751kU/L, and a viral hepatitis screen showed chronic hepatitis C virus (HCV) infection and evidence of previous hepatitis B viral infection." (PMID 28193171, 2017).
viral hepatitis (continued). "Seven independent predictors of the DLR nomogram model were as follows: viral hepatitis, absence of washout, absence of capsule, necrosis, AFP, habitat radiomics score, and DL score." (PMID 41428280, 2025). "Intriguingly, in subgroups defined by younger age (<65 years), absence of viral hepatitis, and high AFP levels, dual ICIs therapy appeared to offer a greater survival advantage." (PMID 41451207, 2025). "Our patient had a history of alcohol abuse, but not viral hepatitis, and his AFP levels were within the normal range, making the diagnosis of metastatic HCC in the PPS particularly challenging." (PMID 38968748, 2024). "Our meta-analysis showed the clinico-pathological characteristics of viral hepatitis positivity, AFP less than 400 ng/ml, ECOG 0, MVI, no EHS, and positive PD-L1 expression correlated with preferable ORR to immunotherapy." (PMID 37598406, 2023). "cHCC-CCA patients showed similarities with HCC regarding male predilection, status of viral hepatitis, serum alpha-protein (AFP) level and nontumor histology." (PMID 36672443, 2023). "A complicating issue in studies of AFP dynamics and determination of AFP slope over time is reliability of AFP measures in the setting of variable locoregional therapies, a lack of accounting for viral hepatitis status, and other issues." (PMID 36290870, 2022). "Our results showed that pre-operative factors, such as recipient and donor age, recipient and donor sex, viral hepatitis, serum AFP, tumor status, Child-Pugh score, and NLR were not potential predictors in the univariate analysis." (PMID 35735419, 2022). "Yet, significant elevations of AFP are commonly seen in nonhepatic malignancies and benign conditions, such as acute and chronic viral hepatitis." (PMID 26640716, 2015). "Patients: HCC vs. (healthy and viral hepatitis)Tests: methods for GP73and AFP test not cleared reportedOutcomes: no usable data." (PMID 22244200, 2012). "However, AFP has limited sensitivity and specificity, particularly in early-stage HCC, and false elevations can occur in conditions such as active hepatic inflammation (e.g., viral hepatitis) or other liver masses like cholangiocarcinoma." (PMID 40978045, 2025). "The results showed that pre-operative factors, such as recipient and donor age, recipient and donor sex, viral hepatitis, and serum AFP, were not potential predictors in the univariate analysis, but MELD score ≥ 20, NLR ≥ 5, pre-LT locoregional treatment before LT were." (PMID 35735419, 2022). "Sonographic score, AFP, and viral hepatitis were used to construct a predictive nomogram." (PMID 34692513, 2021). "However, the prognostic role of serial changes in serum AFP levels following TACE has been controversial as not all HCC produce AFP, and false positive results not infrequently occur such as in active viral hepatitis." (PMID 32471447, 2020). "More importantly, IL-35 robustly dampened IFN-γ secretion by AFP-specific liver-resident CD8+ T cells purified from both non-tumor and tumor site, further revealing the immunosuppressive characteristic of IL-35 to CD8+ T cells in non-viral hepatitis-related HCC." (PMID 31134088, 2019). "Moreover, correlation analysis between the expression of lncRNAs and clinicopathological parameters revealed that DDX11-AS1 was intimately associated with tumor recurrence (p < 0.05), tumor stage (p < 0.05), alpha fetoprotein (AFP) level (p < 0.0001) and viral hepatitis (p < 0.001)." (PMID 29599483, 2018). "Viral hepatitis markers were negative and serum alpha fetoprotein was within reference range." (PMID 27446853, 2016). "The alpha-fetoprotein (AFP) level was 1.38ng/mL, and serological tests for viral hepatitis were all negative." (PMID 41211439, 2025). "For example, AFP has been shown to have high sensitivity for the detection of HCC, with optimal cut-off values lower in those receiving antiviral therapy for chronic viral hepatitis compared with those not receiving antiviral therapy." (PMID 39578653, 2024).
viral hepatitis (continued). "Clinical parameters including age, gender, viral hepatitis; presence of MVI, EHS, and adverse effects; values of AFP; and different TKIs had non-significant effects." (PMID 36013120, 2022). "However, the sensitivity of these biomarkers in the detection of early HCC or small lesions is limited, and AFP levels may also be elevated in other malignancies (such as cholangiocarcinoma or colon cancer), as well as during flare-ups of chronic viral hepatitis, also in the absence of HCC." (PMID 26854169, 2015). "As yet, none has proved superior to AFP in performance, but in combination some may have complimentary roles in HCC arising on a background of viral hepatitis." (PMID 18638391, 2008).
hepatoblastoma (94 papers, 1986 to 2026). Hepatoblastoma (HB) is a malignant hepatic tumor and is the most common pediatric liver cancer. "The subsequent ROC curve analysis further validated the diagnostic value of AFP in distinguishing hepatoblastoma patients from healthy individuals, with an AUC of 0.9905 (p < 0.0001)." (PMID 40271711, 2025). "In Case 3, extremely low AFP (< 100) combined with weak β-catenin positivity initially prompted high-risk hepatoblastoma therapy following SIOPEL guidelines." (PMID 40560480, 2025). "The differential diagnostic value of PIVKA-II and AFP in hepatoblastoma from hemangioendothelioma was further assessed, AUROC of PIVKA-II (cut-off value 47.1mAU/mL) and AFP (cut-off value 560 ng/mL) was 0.876 and 0.743." (PMID 38622445, 2024). "Risk factors for tumor recurrence in patients with hepatoblastoma were higher AFP before transplant (AFPpre-LTX), a low ratio of AFPmax to AFPpre-LTX and salvage transplantation." (PMID 36832331, 2023). "This prospective observational study sought to ascertain the feasibility of ctDNA detection in patients with hepatoblastoma and explore its associations with established clinical indicators and biomarkers, including serum Alpha-fetoprotein (AFP)." (PMID 38201440, 2023). "Hepatoblastoma (HB) is associated with elevated levels of alpha-fetoprotein (AFP) at diagnosis and varied histological patterns." (PMID 36672416, 2023). "A recent study has found the diagnostic value of AFP for recurrence of hepatoblastoma, showing that AFP elevation was specific at detecting relapse after CR." (PMID 34843510, 2021). "In most cases of MHL, the α fetoprotein (AFP) level is within the normal limits, only in a few cases, increased AFP has been described which usually causes misdiagnosis of hepatoblastoma." (PMID 34131505, 2021). "Two of three patients who fulfilled the high‐risk hepatoblastoma criteria based on low AFP level had PRETEXT IV disease." (PMID 32379933, 2020). "Younger diagnostic age and lower alpha-fetoprotein levels after neoadjuvant chemotherapy and are predictive of better overall and native liver survival in hepatoblastoma patients." (PMID 28851352, 2017). "A diagnosis of hepatoblastoma at ≤1.25 years of age was also associated with an AFP level < 1200 ng/mL after SIOPEL neoadjuvant chemotherapy (Odds ratio: 8) in this study." (PMID 28851352, 2017). "Presence of membranous EpCAM with nuclear β-catenin and younger diagnostic age of hepatoblastoma are predictive of serum alpha-fetoprotein levels drop after chemotherapy." (PMID 28851352, 2017). "Diagnosis of hepatoblastoma at ≤1.25 years of age was also associated with an AFP level < 1200 ng/mL after neoadjuvant chemotherapy (Odds ratio, 8; 95% CI: 1.33–48.18; P = 0.02) in this study." (PMID 28851352, 2017). "It is noteworthy here too that it has recently become apparent that some ‘non-AFP secreting hepatoblastomas’, previously deemed higher risk disease, are actually hepatic rhabdoid tumours." (PMID 27526937, 2016). "Third, enhanced early detection strategies, including improved awareness among healthcare providers about hepatoblastoma presentations and the use of alpha‐fetoprotein (AFP) screening in high‐risk populations, have facilitated earlier diagnosis and treatment initiation." (PMID 40827443, 2025). "Small cell undifferentiated (SCU) histology and alpha-fetoprotein (AFP) levels below 100 ng/mL have been reported as poor prognostic factors in hepatoblastoma (HB); subsequent studies reported SMARCB1 mutations in some SCU HBs confirming the diagnosis of rhabdoid tumor." (PMID 36672416, 2023). "Screening for hepatoblastoma by liver palpation, abdominal ultrasound, and serum alpha-fetoprotein every 3–6 months until the age of 5 years or every 2 years until the age of 7 years has been proposed." (PMID 41214301, 2026). "UESL misinterpretation as anaplastic hepatoblastoma can arise from overlapping immunohistochemical markers and low alpha-fetoprotein (AFP) levels." (PMID 40560480, 2025).
hepatoblastoma (continued). "In case of Hepatoblastomas (HB), alpha-fetoprotein (AFP) is an established marker for diagnosis, being positive in about 90% of patients." (PMID 40504251, 2025). "One patient with hepatoblastoma received six cycles before the alpha-fetoprotein level started to rise." (PMID 40941020, 2025). "Differentiation can be done based on blood works, such as alpha fetoprotein in hepatoblastoma and positive hydatid cyst blood workup." (PMID 40336797, 2025). "Serum alpha-fetoprotein (sAFP) values were significantly higher in hepatoblastoma patients (n=9), compared to the HCC (n=10) (P=0.002)." (PMID 39961817, 2025). "In the Rome cohort, one patient developed HCC, and another had hepatoblastoma with an AFP level below 5 ng/mL." (PMID 40332516, 2025). "Serum AFP(RRID:NSRRC_0028) levels can increase before changes are detectable through abdominal imaging in patients with hepatoblastoma." (PMID 41333206, 2025). "Pure radiology-based diagnostic accuracy was 81.8% (95% CI, 72.2–89.2%), which increased to 92.1% (95% CI, 84.3–96.7%) (P-value > 0.05) after AFP correlation, with one hepatoblastoma misdiagnosed as a rhabdoid tumor." (PMID 38831055, 2024). "In our study, the sensitivity, specificity and AUROC of PIVKA-II in the diagnosis of childhood hepatic tumors and in the differentiation of hepatoblastoma from benign hepatic tumors were all higher than AFP." (PMID 38622445, 2024). "Blood tests (clinical, biochemical, coagulation profile, and AFP for hepatoblastoma patients) and abdominal ultrasound were performed for all patients." (PMID 39906731, 2024). "One of these lesions was resected at age 3 months because postnatal contrast-enhanced CT and MRI suggested hepatoblastoma with AFP increase." (PMID 38172842, 2024). "The subgroup analysis showed that PIVKA-II and AFP levels in patients with malignant hepatoblastoma were higher than those with the benign hemangioendothelioma, in our study." (PMID 38622445, 2024). "Apart from the indeterminate lesions, one case of pathologically proven ruptured hepatoblastoma with enlarged nodes and mild ascites with serum AFP of 8 ng/mL was incorrectly labeled as rhabdoid tumor." (PMID 38831055, 2024). "The radiologists classified the lesion as hepatoblastoma, infantile hemangioma, mesenchymal hamartoma, rhabdoid tumor, or indeterminate, first based purely on imaging and then after alpha-fetoprotein (AFP) correlation." (PMID 38831055, 2024). "Hepatoblastoma screening in these children is advised based on the following schedule: abdominal ultrasound and serum alpha-fetoprotein (AFP) every three months for the first year, every two months for the second year, and every three months thereafter." (PMID 39156381, 2024). "In this paper, the pathological staining findings of Cytokeratin 17, AFP, Hepatocyte and Glypican 3 in the tumor tissue clearly indicated a fetal epithelial subtype of hepatoblastoma." (PMID 38819760, 2024). "Hepatoblastoma is commonly characterized by markedly elevated serum AFP levels, a solid appearance, and calcifications." (PMID 39737275, 2024). "The six lesions included two hepatoblastoma with borderline AFP levels, a mesenchymal hamartoma with more solid and less cystic components, and three rhabdoid tumors." (PMID 38831055, 2024). "Two out of fourteen indeterminate cases had single-phase imaging (one hemangioma and one hepatoblastoma) and the case of hepatoblastoma remained indeterminate after AFP correlation." (PMID 38831055, 2024). "Meanwhile, other known markers of hepatoblastoma, including AFP, DLK1, and GPC3, were upregulated in the epithelial (similarly in both fetal and embryonal) but not mesenchymal components." (PMID 39567523, 2024). "Her serum AFP level increased rapidly to 134392 ng/ml at the age 4 years and 10 months, when a pre-operative biopsy was conducted on the hepatic mass, and hepatoblastoma was suspected on pathological analysis." (PMID 38819760, 2024).